CRP (C-reactive protein)
Diseases named in the same sentence as CRP in open-access papers (continued):
Sharing a sentence is not in itself a finding about the gene and the disease.
Hypertension (continued). "Meanwhile, age, male, history of hypertension (HP), myoglobin (MYO), creatine kinase-MB (CK-MB), high-sensitivity troponin-I (Hs-TnI), urea, creatinine, white blood cell (WBC), lymphocytes (LYM), c-reactive protein (CRP) and procalcitonin (PCT) were correlated with the risk of in-hospital death." (PMID 32293449, 2020). "On average, the analytic sample was overweight (27.8 ± 5.7 kg/m2), had stage 2 hypertension (142 ± 22 mm Hg in systolic blood pressure), hyperlipidemia (224.0 ± 52.7 mg/dL total cholesterol; 189.2 ± 179.2 mg/dL triglycerides), and elevated levels of CRP (7.9 ± 14.0 mg/L)." (PMID 31683657, 2019). "Subjects with IR differed significantly from those non-IR by age, total cholesterol, fasting glucose, fasting insulin, glycosylated hemoglobin, and prevalence of hypertension (p < 0.05), but not by sex, drinking, smoking, CRP, and other cardiovascular risk factors." (PMID 31249520, 2019). "Furthermore, overweight/obese individuals showed positive correlation of both plasma C-Reactive Protein and triglyceride/HDLc-index with LGI-Ob; and high LGI-Ob score was associated with greater hypertension (p = 0.047), Type 2 diabetes (p = 0.026), and metabolic risk (p = 0.021)." (PMID 30704070, 2019). "However, the results of the multivariate regression analysis with htTKV as the dependent variable, including hypertension, CRP, eGFR, age, time since diagnosis, VDR and 25(OH)D adjusted for season of the year showed that only the first three parameters were independent predictors of the former." (PMID 31179282, 2019). "In turn, proinflammatory adipokines and CRP might express their action on endothelial cells compromising their proliferative rate and angiogenic potential, which may contribute to the decline of vascular health and development of symptoms such as hypertension." (PMID 30510967, 2018). "Furthermore, Magen and colleagues found a significant positive correlation between systolic blood pressure and CRP levels, with significantly higher levels in the resistant hypertension group compared with the controlled hypertension group (6.9 ± 5.8 versus 4.2 ± 4.8, P = 0.021)." (PMID 27433355, 2016). "Furthermore CRP was found to be a predictor of future development of hypertension." (PMID 27433355, 2016). "Finally, multivariate regression analysis revealed that after extensively adjusted for potential confounding factors including age, smoking, duration of hypertension, CRP, BMI, and anti-hypertensive medicines, Lp-PLA2 activity was still significantly associated with RH." (PMID 26801405, 2016). "Elevated CRP level may lead to total stroke and hypertension." (PMID 26989902, 2016). "In addition, in animal models treatment of hypertension with Angiotensin-II Receptor Blockers (ARBs) reduces the level of inflammatory activation in vessels, because this drug can reduce the circulating levels of some inflammatory mediators and CRP." (PMID 25996882, 2015). "In Western societies, chronic stress has previously been associated with hypertension and biomarkers of inflammation that indicate risk of cardiovascular disease (CVD), including an elevated erythrocyte sedimentation rate and higher levels of C-reactive protein (CRP)." (PMID 25214482, 2014). "The associations of rs2274700 (A473A) with DBP (P = 2.1×10−3) and SBP (8×10−5), and hypertension risk (7.9×10−3)were significant only in individuals with low CRP levels (<2.0 mg/l), but not in those with elevated CRP levels (≥2.0 mg/l) (P≥0.0807, P for interaction: 0.001–0.047)." (PMID 22848687, 2012). "However, there was a reduction of 18% in the absolute socioeconomic gradient when looking at subjects with CRP-levels < 3 mg/L, and of 69% when looking at a low-risk population with no smoking, hypertension, or hyperlipidemia." (PMID 18518944, 2008). "In the present study, CRP concentrations and MDA levels were markedly elevated in hypertensive rats, reflecting the well-established link between high CRP and hypertension." (PMID 41515269, 2026).
Hypertension (continued). "After adjusting for gender, age, BMI, course of disease, hypertension, smoking and alcohol consumption (model 2) as well as HbA1c, HOMA-IR, C-reactive protein and TG (model 3), similar results were obtained." (PMID 41716315, 2026). "Women with higher triglycerides, sensitivity CRP, and lower HDL-C were more likely to develop hypertension post-delivery." (PMID 40012983, 2025). "Several investigated potential confounders showed expected trends with higher atherogenic and lower anti-atherogenic lipids and Apos with older age, urban locality, increased CRP levels, diuretic use, HIV positive status and hypertension." (PMID 40375303, 2025). "Their mortality risk is critically amplified by modifiable factors including smoking (HR = 5.27), hs-CRP ≥3 mg/L (HR = 10.15), HDL-C <1.3 mmol/L (HR = 17.94), and comorbidities (hypertension HR = 3.69; dyslipidemia HR = 4.97; MetS HR = 12.89)." (PMID 40969377, 2025). "Evidence confirms that women with higher triglycerides, sensitivity CRP, and lower HDL-C were more likely to develop hypertension post-delivery." (PMID 40012983, 2025). "We performed multivariate binary logistic regression in the groups (outcome variable: hypertension vs. non-hypertension) with variables identified as significantly different: VLDL, triglycerides, CRP, WBC, NLRP3 (serum), and IL-1β B (saliva)." (PMID 40572711, 2025). "Further, inflammatory markers such as C-reactive protein (CRP) are found to be elevated in both depression and hypertension, which suggests a common inflammatory factor between both conditions." (PMID 40851703, 2025). "A significant relationship was found between malignancy, hypertension, low albumin, NLR, and CRP values with mortality." (PMID 40521831, 2025). "This study demonstrated that among the recruited patients with hypertension visiting our cardiovascular outpatient department, significantly higher prevalence rates of DM and higher levels of PCS and CRP were noted in those diagnosed with PAD measured by ABI." (PMID 40361914, 2025). "Higher NHR values were correlated with age, sex, hypertension, intraventricular hemorrhage, GCS score, glucose levels, C-reactive protein, absolute lymphocyte count, albumin levels, and absolute monocyte count." (PMID 40800139, 2025). "Prior investigations reported links between ED and multiple RFs, namely, BMI, smoking habit, hypertension, DM, CVD, and certain inflammatory indexes, such as, leukocytes and CRP." (PMID 41324115, 2025). "Higher values were found in the periodontitis and hypertension group than in healthy individuals for VLDL (p = 0.001), triglycerides (p = 0.001), CRP (p = 0.003), WBC (p = 0.007), blood sugar (p = 0.002), total cholesterol (p = 0.003), and LDL (p = 0.010)." (PMID 40572711, 2025). "Among the four BMI-metabolic phenotypes, the MUOO group had the highest average values for BMI, WC, SBP, DBP, HbA1c, FBG, TG, and CRP, the lowest average HDL-C, and the highest proportions of individuals with hypertension and dyslipidemia (all p < 0.001)." (PMID 40917090, 2025). "The highest concentrations of CRP, WBC, total cholesterol, LDL, VLDL, and triglycerides were observed in the group of patients with both hypertension and periodontitis." (PMID 40572711, 2025). "After performing LASSO regression analysis on clinical factors, five variables were selected (λmin: 0.031, λ1SE 0.103), which were hypertension, hemoptysis volume, PLT, CRP, and PT." (PMID 41488072, 2025). "The first multivariate analysis included BMI, hypertension and CVD presence, glucose, TG, HDL-cholesterol, ALT, GGT, CRP, TAS, TOS, IMA and miR-21 as covariates, while the second multivariate analysis included miR-34a instead of mir-21." (PMID 40141039, 2025). "Significant differences among the four groups were also found for VLDL (p = 0.002), triglycerides (p = 0.002), CRP (p = 0.004), and WBC (p = 0.008), again with the highest values observed in the periodontitis and hypertension group." (PMID 40572711, 2025).
Hypertension (continued). "The findings showed that there were significant differences in gender, PIR, BMI, hypertension, Hb, HCT, MCH, RDW, and albumin between the High and Low CRP groups (P < 0.05)." (PMID 40087374, 2025). "The levels of inflammatory factors, such as C-reactive protein (CRP) and tumor necrosis factor-α (TNF-α), are positively correlated with hypertension." (PMID 41347150, 2025). "Clinical studies support that both C-reactive protein (CRP) levels and white blood cell (WBC) counts mediate the relationship between periodontal disease and high blood pressure." (PMID 40002786, 2025). "For instance, the model shows a connection between C-reactive protein (CRP) and high blood pressure." (PMID 41154955, 2025). "Female participants with incident HUA had higher age; higher prevalence of hypertension; higher SBP, DBP, SUA, CRP, serum creatinine, TC, TG, FPG, HbA1c, and BUN; and lower HDL." (PMID 38405154, 2024). "Our results indicated that cardiovascular disease and CRP log were positively correlated with MIS results, whereas age, hypertension, hemoglobin level, albumin level, phosphorus level, and BMI were negatively correlated with SGA results." (PMID 39683409, 2024). "Univariate analysis revealed a significant correlation between unfavorable outcome and age, arterial hypertension, regular medication with CCB and anticoagulants, Fisher grades III–IV, aneurysm clipping, and admission CRP." (PMID 38376665, 2024). "In the diabetic group, AIS patients with HbA1c < 6.0% had the highest levels of Scr, C-reactive protein, the lowest HGB, and the highest percentage of hypertension." (PMID 38433248, 2024). "In the high NAR group, neutrophil counts, HbA1c, FPG, BNP, WBC, PLT, ALT, CRP, UA, Scr, LVDd, LVDs, the proportion of males, infection, prior MI, PCI, hypertension, hyperuricemia, diuretics and statin use were significantly higher." (PMID 38649986, 2024). "Multivariate regression analysis revealed that hypertension, decreased lymphocyte count, and elevated LDH, CRP, and AST levels (grade 2 and grade 3 relative to grade 1) were the significant predictive variables." (PMID 39194933, 2024). "The top 5 important feature of Model 2 were CRP, CK, T2DM, hypertension and the number of oral medications." (PMID 39135800, 2024). "No notable distinctions were noted between both cohorts concerning age, BMI, SBP, DBP, history of hypertension, drinking history, history of family CVD, FBG, eGFR, and CRP." (PMID 38704561, 2024). "Significant differences were observed between the two groups in terms of age, hypertension, sepsis, renal injury, and various laboratory indicators, including WBC, PLT, Ca2+, CRP, hemoglobin, albumin, and creatinine (P<0.05)." (PMID 38903514, 2024). "Separate adjustments were made for age, sex, hypertension (including BMI, SBP, CRP, TG, HCY, and LDL-C), and LDL-C (including BMI, SBP, CRP, TG, and HCY) groups." (PMID 38254149, 2024). "No substantial variances were detected across the groups concerning the incidence of family CVD and hypertension, as well as levels of HDL-C, FBG, HbA1C, eGFR, and CRP." (PMID 38704561, 2024). "Mediterranean and Dietary approaches to stop hypertension (DASH) diets, which are rich in vegetables, fruits, whole grains, nuts, legumes, olive oil, and fish, reduce C-reactive protein (CRP) and systemic inflammation compared to unhealthy diets." (PMID 38898498, 2024). "Patients in the NSCLC group had a higher prevalence of smoking, hypertension and COPD, and elevated CRP levels compared to controls." (PMID 39835329, 2024). "Firstly, in a group without DM, consisting of 8,224 participants, the analysis adjusted for factors such as age, CRP, eGFR, sex, HDL-c, LDL-c, UA, CLD, PLT, Cystatin C, hypertension, HBA1C, CKD, smoking, drinking status." (PMID 38402161, 2024).
Hypertension (continued). "Additionally, incorporating clinical data such as blood test results (e.g., white blood cells WBC), levels of proteins like D-dimer, ferritin, or CRP, or information about underlying conditions (e.g., hypertension) did not significantly improve prediction of disease severity." (PMID 39375263, 2024). "Some patients with persistent hiccups had elevated C-reactive protein, D-Dimer, LDH, and hypertension." (PMID 39221325, 2024). "After adjusting for sex, age, BMI, disease course, hypertension, smoking, and drinking (model 2) as well as HbA1c, HOMA-IR, C-reactive protein, and TG (model 3), similar results were obtained." (PMID 38239233, 2024). "These factors encompass hypertension, smoking, increased body mass index (BMI), elevated platelet count, hematocrit, NLR, PLR, and C-reactive protein (CRP)." (PMID 38302950, 2024). "Given these insights, our study treated metabolic disorders such as hypertension, T2DM, hyperlipidemia, and elevated CRP as potential mediators linking sarcopenia to IS." (PMID 38757378, 2024). "These factors include hypertension, smoking, increased BMI, hematocrit, Platelet-to-Lymphocyte Ratio (PLR), and C-reactive protein (CRP)." (PMID 38302950, 2024). "Age, BMI, comorbidities (hypertension, hyperlipidemia, pulmonary infection), LVEF, Cr, CRP, TG, and time between imaging examinations were all significantly different between the two groups." (PMID 39068452, 2024). "After adjustment for sex, age, BMI, disease course, hypertension, smoking, drinking, HbA1c, HOMA-IR, C-reactive protein, and TG, similar results were obtained (OR 1.59, 95% CI 1.06-2.38, model 2; OR 1.6, 95% CI 1.04-2.46, model 3)." (PMID 38239233, 2024). "In women aged 65 and above, the relationship between inflammatory markers and blood pressure was consistent, with hs-CRP and WBC emerging as predictors of high blood pressure." (PMID 38720047, 2024). "In this study, the analysis of 1022 patients with chronic non-genotype 3 HCV infections indicated that those who had CKD had higher prevalences of hypertension and liver steatosis, and higher levels of BMI, HOMA-IR, serum lipids, CAP, and CRP, but lower eGFR." (PMID 37400794, 2023). "While inflammation is closely intertwined with the development of hypertension and HHD, a probable relationship exists between CRP and HHD, as shown in our extensive sensitivity and multivariable analyses." (PMID 37298077, 2023). "The baseline risk model includes age, sex (male), BMI, SBP, DBP, smoking, hypertension, dyslipidemia, prior PCI, TC, LDL-C, eGFR, Cr, CRP and SUA." (PMID 37653411, 2023). "Other factors (hypertension, smoking, increased BMI, decreased dyslipidemia and high platelet count, hematocrit, PLR and CRP) significantly increase in patients with CSF and can be used as predictors of CSF." (PMID 37161453, 2023). "Age, BMI, ceruloplasmin, clinical status at presentation (no significant CAD, stable CAD, unstable angina pectoris, STEMI, NSTEMI), CRP, GFR, HDL-cholesterol, hypertension, LDL-cholesterol, sex, smoking status, triglycerides, type 2 diabetes." (PMID 37441705, 2023). "Females with higher UA levels were older, and more likely living in urban, having DM, hypertension, dyslipidemia, arthritis, and higher creatinine, LDL-c, CRP, and lower eGFR and HDL-c." (PMID 37513515, 2023). "In this study, it was observed that several risk factors were associated with the H. pylori infection, including age, gender, hypertension, ALP, γ‐GT, total cholesterol, LDL, anti‐SSA/Ro60 positive, hypergammaglobulinemia, and CRP levels." (PMID 37904694, 2023). "In the grades' 1-2 hypertension group, the levels of SUA, glucose, and hs-CRP were lower than those in the grade 3 hypertension group (all P < 0.05)." (PMID 37360061, 2023). "Compared with the NAD group, a higher incidence rate of smoking and hypertension and elevated values of SBP, WBC, D-dimer, NT-proBNP, and CRP were observed in the AD group." (PMID 38188253, 2023).
Hypertension (continued). "The prevalence of hypertension and the LDL-C, hs-CRP, cTnI, CK-MB, and NT-proBNP levels were higher in STEMI patients than that in healthy controls." (PMID 37840751, 2023). "For those patients with hypertension in the severe group, levels of Cr, PCT, CRP, and ESR were significantly increased while levels of PLT and ALB were decreased, where levels of CRP, ESR and ALB were varied both quantitatively and as a categorical variable." (PMID 37790212, 2023). "Similar to the reported studies, various risk factors relevant to the H. pylori infection in patients with pSS were observed, such as female proportion, hypertension, higher total cholesterol, higher LDL, high CRP, and hypergammaglobulinemia." (PMID 37904694, 2023). "Compared with the other two groups, patients with NLPR > 0.5 tended to have a history of Hypertension, hyperlipidemia, higher levels of systolic BP, heart rate, APTT, creatinine, INR, Lactate, PT, RBC, RDW, urea, CRP and Mg." (PMID 37616313, 2023). "Patients were evaluated pre-operatively for characteristics of metS and MUO (HbA1c, HOMA, CRP, BMI, fasting glucose, LDL, TG, HDL and the presence of arterial hypertension)." (PMID 37371690, 2023). "The aim of this study was to investigate the relationship between Hypersensitive C-reactive protein (hs-CRP) and left ventricular hypertrophy (LVH) in elderly community-dwelling patients with hypertension." (PMID 37759159, 2023). "When compared to the Q1 group, subjects in the other groups were more inclined to be more current smokers, current drinkers, and male, had a higher SBP, DBP, BMI, FBG, hs-CRP, TG, LDL-C, TC level, and a higher prevalence of hypertension (P<0.01)." (PMID 37065738, 2023). "In contrast, they had higher values of days of hospitalization, glucose level, LDH, AST, FIB-4, APRI, CRP, platelets, leukocytes, neutrophils, and NLR, as well as more cases of cardiovascular diseases, anemia, kidney diseases, and hypertension." (PMID 36829793, 2023). "Consistent with previous studies, we found that hypertension, WBC, LDL-C, hs-CRP, exo-circ-0020887, and exo-circ-0009590 expression were risk factors for short-term adverse cardiovascular outcomes in univariate Cox regression model." (PMID 37840751, 2023). "The indicators of pro-inflammatory status (C-reactive protein, TNF-α, IL-6), corresponding to the normative range of values, were higher in males than in females both in uncomplicated hypertension and in the presence of HFpEF." (PMID 35997392, 2022). "This study also showed that statin use was higher in the group with normal CRP than in the group with elevated CRP, and although not statistically significant, statin use reduced the risk of hypertension (OR = 0.49,95%CI: 0.25–0.94, p < 0.05) and was protective against hypertension." (PMID 36418968, 2022). "Age, BMI, WC, SBP, DBP, TG, hs-CRP, HbA1c, FBG, uric acid, creatinine, incidence of hypertension and prior stroke were all higher in the lower eGDR cluster when contrasted to the higher eGDR cluster, whereas HDL-C and eGFR were lower." (PMID 36203208, 2022). "Patients in the high median SII and NLR groups had hypertension, high PLR, hs-CRP, WBC, FIB, GLUC, mean IMT, max IMT, and Gensini score but low eGFR and HDLC." (PMID 35371012, 2022). "Consistently, our work reveals that the level of CRP was elevated and positively correlated with SBP, corroborating the notion that hypertension is an inflammatory condition." (PMID 35571179, 2022). "Correlations of gene expression in patients were found with levels of serum uric acid (sUA), serum creatinine, C-reactive protein (CRP), triglycerides, body mass index (BMI), kidney disease, hypertension, and metabolic syndrome." (PMID 35505381, 2022). "Age, sex, BMI, systolic blood pressure, diastolic blood pressure, heart rate, eGFR, history of (hypertension, CAD, T2DM, AF), prescription of (ACEI, β-blockers, digoxin, diuretic, bronchodilator), CRP, and NT-proBNP." (PMID 36204571, 2022).